IGSF21 (immunoglobin superfamily member 21)
Description:
Involved in synaptic inhibition in the brain. Selectively regulates inhibitory presynaptic differentiation through interacting with presynaptic NRXN2.
Synonyms: MGC15730; RP11-121A23.1
Tractability: Antibody: UniProt places it where antibodies can reach, with medium confidence; UniProt predicts a signal peptide or a membrane-spanning region; its Gene Ontology location is reachable by antibodies, with medium confidence. PROTAC: its protein half-life has been measured.
Gene: Protein-coding gene on chromosome 1 (18,107,710 to 18,378,483, forward strand). Ensembl gene ENSG00000117154.
Subcellular location: Postsynaptic cell membrane
Gene Ontology:
Biological process: synapse maturation; trans-synaptic signaling, modulating synaptic transmission
Cellular component: cell junction; external side of plasma membrane; inhibitory synapse; plasma membrane; postsynaptic density membrane; postsynaptic membrane; presynaptic membrane
Genetic constraint (gnomAD): Loss-of-function variants: 24 observed, 39.33 expected, observed/expected ratio (o/e) 0.61, 90% interval 0.44 to 0.86. The upper end of that interval is the gene's LOEUF score, 0.86, which puts it in group 3 of 6, group 1 being the genes least tolerant of losing a copy. Missense variants: 608 observed, 656.62 expected, observed/expected ratio (o/e) 0.93, 90% interval 0.87 to 0.99. Synonymous variants: 278 observed, 270.18 expected, observed/expected ratio (o/e) 1.03, 90% interval 0.93 to 1.14.
Homologues: Orthologues: chimpanzee IGSF21 (99% identical), macaque IGSF21 (99% identical), rat Igsf21 (95% identical), dog IGSF21 (94% identical), mouse Igsf21 (94% identical), pig IGSF21 (93% identical), guinea pig IGSF21 (88% identical), rabbit IGSF21 (83% identical), tropical clawed frog igsf21 (79% identical), zebrafish igsf21a (70% identical), zebrafish igsf21b (64% identical). Paralogues in human: CNTN3 (22% identical), NEO1 (22% identical), ROBO1 (21% identical), ROBO2 (21% identical), CNTN6 (21% identical), ROBO3 (21% identical), DCC (21% identical), L1CAM (21% identical), NRCAM (20% identical), CNTN4 (20% identical), SDK2 (20% identical), SDK1 (19% identical), and 24 more.
Diseases named in the same sentence as IGSF21 in open-access papers:
IGSF21 is named in the same sentence as 9 diseases in open-access papers, as found by Europe PMC text mining. Sharing a sentence is not in itself a finding about the gene and the disease. The quoted sentences say what the papers report.
anxiety disorder (1 paper, 2017). A category of psychiatric disorders which are characterized by anxious feelings or fear often accompanied by physical symptoms associated with anxiety. "Therefore, it would be important for future studies to more comprehensively characterize behavioral phenotypes of Igsf21−/− mice and/or region-specific Igsf21 knockout mice and also to sequence the IGSF21 gene locus in human patients with schizophrenia, ASDs and anxiety disorders." (PMID 28864826, 2017).
diabetic retinopathy (1 paper, 2012). "Its usefulness in generating novel scientific hypotheses is demonstrated through the study of IGSF21, a little-known gene that was recently identified to be associated with diabetic retinopathy." (PMID 23209562, 2012).
tumor (2 papers, 2023 to 2025). "Furthermore, these two cases shared a common five-member mutant cell surface receptor signature as well (DSCAM, IGSF21, GHR, GRINA2 and RP1), suggesting that they may also have been involved in the massive antitumoral response to the primary tumor." (PMID 36980598, 2023).
IGSF21 also shares sentences with these, for which no sentence is quoted: asthma (1 paper); cancer (1); glioma (1); infection (1); schizophrenia (1); virus infection (1).